CCK (cholecystokinin)
Diseases named in the same sentence as CCK in open-access papers (continued):
Sharing a sentence is not in itself a finding about the gene and the disease.
infection (9 papers, 2013 to 2024). The state of being infected such as from the introduction of a foreign agent such as serum, vaccine, antigenic substance or organism. "The peak of severity of intestinal inflammation was observed 9 days post-infection, which coincided with reduced food intake, weight loss, and CCK upregulation." (PMID 33803651, 2021). "In the present study, we clarified the whole-brain, direct, monosynaptic inputs to CCK neurons in the SCN using cell-type specific infection and retrograde spread of a modified rabies virus." (PMID 30455627, 2018). "Some labeling of centrifugal fibers in the GCL of the contralateral OB was seen following P3 injection, which presumably arises from retrograde infection of bilaterally projecting CCK-expressing neurons in the anterior olfactory nucleus." (PMID 26594154, 2015). "Infection with the intestinal parasites Ascaris suum and Trichostrongylus colubriformis results in hypophagia that is coupled with an increase in cholecystokinin (CCK) released from I-cells; a subset of intestinal epithelial enteroendocrine cells (EECs)." (PMID 23349631, 2013). "Our findings are in agreement with these observations, but substantially advance those by showing that in addition to PV and SST inhibitory cells, GABAergic neurons expressing nNOS, NPY, and CCK can be also a subject of infection by CaMKIIα promoter-controlled constructs." (PMID 36963833, 2023). "We were also able to drive expression of GCaMP in AON-OB projection neurons via retrograde infection with the same virus after injection into the OB of young (postnatal day 1–3) (7 mice) or adult Chrna7-Cre (2 mice) animals, as previously reported for cholecystokinin (CCK)-expressing neurons in AON." (PMID 25071454, 2014). "Infection can affect the ENS and potentially alter regulating gut and brain peptides and hormones like peptide YY (PYY), glucagon-like peptide-1 (GLP-1), cholecystokinin (CCK), leptin, or ghrelin." (PMID 39066248, 2024). "Reduced food intake was further observed 25 days post-infection in the absence of CCK upregulation, due to an extraintestinal inflammatory response induced by T spiralis larvae encyst in the skeleton muscle." (PMID 33803651, 2021). "Through the infection of genetically modified mice lacking cholecystokinin, Tumor necrosis factor α receptors and T and B-cells, we observed a biphasic hypophagic response to infection resulting from two separate immune-driven mechanisms." (PMID 23349631, 2013).
metabolic disorders (9 papers, 2015 to 2026). "This molecule represents a preliminary foray into GLP-1:CCK fusion peptides, highlighting the potential utility of this approach as an example of combination therapy to treat metabolic disease." (PMID 29782892, 2018). "Expanding the knowledge on how CCK affects tissue function in individuals with metabolic disorders could provide an opportunity for the development of new and more effective treatment methods." (PMID 39408213, 2024). "In metabolic disorders, baicalin can balance intestinal flora composition, increase the production of SCFAs, and interact with intestinal cells to induce the production of GLP-1, CCK, GIP, and incretin." (PMID 37764277, 2023).
gastrointestinal disorders (5 papers, 2013 to 2025). "CCK release is associated with symptoms in normal weight gastrointestinal disorders and induces motility disturbances associated with complaints." (PMID 23349895, 2013). "The cholecystokinin (CCK) signaling pathway plays an important role in a variety of digestive diseases." (PMID 39948335, 2025). "CCK plays a role in the pathogenesis of gastrointestinal disorders." (PMID 23349895, 2013).
cardiovascular disease (3 papers, 2016 to 2025). "Higher levels of CCK-8 were observed in individuals with cardiovascular disease (p = 0.067), but this result was not statistically significant." (PMID 40005054, 2025).
gastrointestinal tumors (2 papers, 2022 to 2024). "Galectin-9 mainly plays a role in growth regulation in gastrointestinal tumors, characteristically by upregulating CCK-18." (PMID 36358792, 2022).
inflammation (2 papers, 2015 to 2021). Aberrant reaction of the microcirculation characterized by movement of fluid and leukocytes from the blood into extravascular tissues. "We also examined the effects of transient neonatal gastric inflammation on ghrelin, CCK and VIP expressions; the brain–gut axis response to stress; and the mechanism of XSLJZD on FD." (PMID 26508134, 2015).
brain disorder (1 paper, 2023). A disease affecting the brain or part of the brain. "We identified a novel CCK receptor, GPR173, localized in the CCK-GABA synapses and mediated the enhancement of the GABA inhibition effect, which might represent a promising therapeutic target for brain disorders related to excitation and inhibition imbalance in the cortex." (PMID 36813575, 2023).
CCK also shares sentences with these, for which no sentence is quoted: mental disorder (5 papers); bipolar disorder (4); breast carcinoma (4); Glucose intolerance (3); Hyperinsulinemia (3); liver disease (3); airway hyperresponsiveness (2); alcoholism (2); diabetic autonomic neuropathy (2); esophageal cancer (2); gall bladder (2); gallbladder cancer (2); lung fibrosis (2); medullary thyroid carcinoma (2); neurodegenerative disease (2); ovarian carcinoma (2); parasite infection (2); pediatric tumors (2); small cell lung carcinoma (2); acral melanoma (1); acute cholecystitis (1); adenocarcinoma (1); alcoholic cirrhosis (1); amyotrophic lateral sclerosis (1); Asperger syndrome (1); binge eating disorder (1); bladder carcinoma (1); blue nevus (1); Brain atrophy (1); cardiac diseases (1).
A further 57 diseases each share a sentence with CCK in 1 paper.